LAPTM5 (lysosomal protein transmembrane 5)
Diseases named in the same sentence as LAPTM5 in open-access papers (continued):
Sharing a sentence is not in itself a finding about the gene and the disease.
glioblastoma (4 papers, 2020 to 2024). The most malignant astrocytic tumor (WHO grade IV). "Screening for invasion-associated genes identified lysosomal protein transmembrane 5 (LAPTM5) as a relevant gene involved in the invasion of glioblastoma." (PMID 32582531, 2020). "Furthermore, we demonstrated that high LAPTM5 expression is associated with improved overall survival in CD40 high-expressing glioblastoma." (PMID 32582531, 2020). "In conclusion, these data demonstrate that LAPTM5 mediates the sensitivity to temozolomide by the inhibition of CD40-induced NFκB pathway activation in CD40-positive glioblastoma cells." (PMID 32582531, 2020). "We here demonstrate that LAPTM5 inhibits tumorigenicity in glioblastoma based on functional in vitro and in vivo experiments and in silico analysis." (PMID 32582531, 2020). "In conclusion, we identified LAPTM5 as a negative regulator of CD40-mediated NFκB signaling in glioblastoma." (PMID 32582531, 2020). "LAPTM5 was relevantly expressed in all glioblastoma cell lines and primary glioblastoma cells tested." (PMID 32582531, 2020). "In order to identify the underlying molecular mechanisms of LAPTM5 function, we aimed to explore the CD40–LAPTM5 interaction in glioblastoma." (PMID 32582531, 2020). "LAPTM5 expression correlated with better overall survival in glioblastoma patients depending on CD40 expression status." (PMID 32582531, 2020). "An in vivo screen for invasion-associated genes in glioblastoma (further unpublished data) identified LAPTM5 as a highly anti-invasive gene in glioblastoma." (PMID 32582531, 2020). "This treatment induced > 6-fold upregulation of LAPTM5 mRNA expression in primary glioblastoma cell lines." (PMID 32582531, 2020). "In this regard, the presented data reasonably suggest LAPTM5 expression status as a potential biomarker for sensitivity to temozolomide treatment in CD40-positive glioblastoma." (PMID 32582531, 2020). "This study describes the inhibiting effects of LAPTM5 on tumorigenicity in CD40-positive glioblastoma and its role as a negative regulator of CD40-mediated NFκB signaling." (PMID 32582531, 2020). "Furthermore, LAPTM5 expression was correlated with a better overall survival in glioblastoma patients, contingent on the CD40 expression status." (PMID 39281638, 2024). "In CD40 positive glioblastoma, LAPTM5 expression could suppress tumor growth by inhibiting CD40-mediated activation of NF-κB." (PMID 36046710, 2022). "Furthermore, based on the presented results, the LAPTM5 expression status provides a potential new biomarker for response to temozolomide treatment in CD40-positive glioblastoma, which merits further evaluation in clinical practice." (PMID 32582531, 2020). "As LAPTM5 was shown to sensitize CD40-positive U87MG glioblastoma cells to temozolomide and inhibited the NFκB pathway, the functional role of potential NFκB-mediated temozolomide resistance in LAPTM5 knockdown cells as well as the connection with CD40 expression was further investigated." (PMID 32582531, 2020). "Therefore, the aims of this study were to characterize the role of LAPTM5 in glioblastoma, to elucidate its interaction with CD40, and to analyze the underlying signaling pathways involved in tumorigenicity." (PMID 32582531, 2020). "Finally, a TCGA analysis revealed that a higher expression of LAPTM5 has a positive effect on survival in CD40-positive glioblastoma patients." (PMID 32582531, 2020). "Additionally, LAPTM5 inhibited the clonogenicity of U87MG glioblastoma cells as LAPTM5 knockdown cells demonstrated a significantly higher clonogenic capacity compared to the respective vector control cells." (PMID 32582531, 2020). "Therefore, LAPTM5 may present as a potential biomarker for the sensitivity of CD40-positive glioblastoma to temozolomide." (PMID 39281638, 2024). "Hence, LAPTM5 may provide a potential biomarker for sensitivity to temozolomide in CD40-positive glioblastoma." (PMID 32582531, 2020).
glioblastoma (continued). "In contrast, a recent study identified LAPTM5 as an inhibitor of clonogenicity and invasiveness of CD40-positive glioblastoma cells." (PMID 34116687, 2021). "LAPTM5 was previously shown to be regulated by the CD40 receptor in immune cells and CD40 is highly expressed in up to 40% of glioblastoma." (PMID 32582531, 2020). "LAPTM5 relevantly inhibits the clonogenicity and the invasiveness of CD40-positive glioblastoma cells." (PMID 32582531, 2020). "In addition, as shown in vitro and in vivo, LAPTM5 sensitizes CD40-positive glioblastoma cells to temozolomide treatment, the standard chemotherapy for glioblastoma patients." (PMID 32582531, 2020). "Our results indicate that CD40 activates the NFκB pathway in glioblastoma cells only in the absence of LAPTM5 expression, leading to enhanced tumorigenicity and resistance against temozolomide." (PMID 32582531, 2020). "Here, for the first time, we could demonstrate the link between CD40 and LAPTM5 in glioblastoma and characterize the role of the CD40–LAPTM5 axis in tumorigenicity." (PMID 32582531, 2020). "However, the role of LAPTM5 had not been assessed in the prototypical invasive tumor glioblastoma so far." (PMID 32582531, 2020).
melanoma (4 papers, 2012 to 2025). A malignant, usually aggressive tumor composed of atypical, neoplastic melanocytes. "How the expression of LAPTM5 in melanoma transformation is regulated and how it affects its malignancy would thus be worthwhile investigating." (PMID 22880058, 2012). "We demonstrate here that LAPTM5 is also expressed in two melanoma cell lines." (PMID 22880058, 2012). "Transcriptome analyses indeed suggest that LAPTM5 is significantly expressed in some but not all melanomas, while poorly in melanocytes (see Geoprofile, Reference series GSE4570)." (PMID 22880058, 2012). "Since the expression of LAPTM5 is restricted to a limited number of cell types, we confirmed by RT-PCR that LAPTM5 is expressed in M10 cells and in another human melanoma cell line (FO-1) and checked that it is not expressed in HeLa and HEK293 human cell lines." (PMID 22880058, 2012). "From other validated targets in this study that have not yet been investigated in melanoma, we would like to point out MRAS, IL1R2, RAB34, LAPTM5, RDH10, and STK32C." (PMID 36139698, 2022).
Alzheimer disease (3 papers, 2019 to 2024). A progressive, neurodegenerative disease characterized by loss of function and death of nerve cells in several areas of the brain leading to loss of cognitive function such as memory and language. "Genome-wide association studies of late-onset Alzheimer’s disease risk predicted OAS1, LAPTM5, ITGAM/CD11b and LILRB4 as four new risk genes for this neurodegenerative disease." (PMID 34943215, 2021). "Furthermore, in the nervous system, aberrant LAPTM5 expression in microglia is correlated with Alzheimer's disease severity." (PMID 39281638, 2024). "Given the previous studies for ITGAM/CD11b, LAPTM5 and LILRB4, it is tempting to speculate that they are involved in phagocytic processes involving synapses which are known to be reactivated during Alzheimer’s disease progression." (PMID 32274467, 2019). "These four genes, OAS1, LAPTM5, ITGAM/CD11b and LILRB4, have not been previously reported as having variants significantly associated with Alzheimer’s disease using traditional GWAS approaches." (PMID 32274467, 2019).
atherosclerosis (3 papers, 2022 to 2025). A disease characterized by the build-up of fatty material and calcium deposition in the arterial wall resulting in partial or complete occlusion of the arterial lumen. "Among the candidate proteins, LAPTM5 was prioritised due to its known association with autophagy‐related atherosclerosis." (PMID 40755163, 2025). "In our study, we utilized several machine learning algorithms to determine that LAPTM5, SLC40A1, TYROBP, CTSB, and PYCARD, which are related to macrophage genes, can act as diagnostic indicators for individuals with atherosclerosis and are linked to immune infiltration in this disease." (PMID 40881888, 2025). "The results demonstrated significantly higher expression levels of LAPTM5, SLC40A1, TYROBP, CTSB, and PYCARD in the serum of atherosclerosis patients compared to the healthy controls." (PMID 40881888, 2025). "This study began with analyzing the GSE100927 and GSE23746 datasets to evaluate the expression levels of five key genes—TYROBP, CTSB, PYCARD, LAPTM5, and SLC15A3—in atherosclerosis-affected samples compared to normal controls." (PMID 40881888, 2025). "Our study highlights the important roles of LAPTM5, SLC40A1, TYROBP, CTSB, and PYCARD in the context of atherosclerosis." (PMID 40881888, 2025).
HIV-1 infection (3 papers, 2021 to 2024). The type species of lentivirus and the etiologic agent of acquired immunodeficiency syndrome (AIDS). "Lysosomal-associated transmembrane protein 5 (LAPTM5) is a major restriction factor against HIV-1 infection of macrophages and DCs, as it is responsible for transporting Env glycoproteins to lysosomes for destruction." (PMID 39205255, 2024). "In primary CD4+ T cells, the re-expression of LAPTM5 contributes to a Vpr-dependent promotion of HIV-1 infection, as was observed in macrophages." (PMID 39281638, 2024). "For this reason, we proposed a theoretical model of how Vpr counteraction of LAPTM5 enhances HIV-1 infection in macrophages." (PMID 34140527, 2021). "Here, we report that Vpr counteracts lysosomal-associated transmembrane protein 5 (LAPTM5), a potent inhibitor of HIV-1 particle infectivity, to enhance HIV-1 infection in macrophages." (PMID 34140527, 2021). "We mechanistically probed how LAPTM5 combats HIV-1 infection by investigating LAPTM5 and the other LAPTM family members LAPTM4A and 4B." (PMID 34140527, 2021). "The presence of Vpr enhances HIV-1 infection by promoting LAPTM5 degradation via the DCAF1/proteasome, thus releasing Env from the Golgi complex traffic to the plasma membrane for HIV-1 progeny assembly." (PMID 34140527, 2021). "Re-expressing LAPTM5 reconstituted the Vpr-dependent promotion of HIV-1 infection in primary CD4+ T cells, as observed in macrophages." (PMID 34140527, 2021). "We explored the mechanisms by which LAPTM5 restricts HIV-1 infection." (PMID 34140527, 2021). "The data obtained from the experiments were derived from a single measurement and repeated in three different healthy donors, suggesting that LAPTM5 may inhibit HIV-1 infection and Vpr can compromise the inhibition." (PMID 34140527, 2021). "Because our data suggest that Vpr counteracts LAPTM5 by inducing its degradation, we decided to investigate whether the Vpr-induced degradation of LAPTM5 promotes the spread of HIV-1 infection among primary MDMs." (PMID 34140527, 2021). "Therefore, the degradation of LAPTM5 may be dependent on the newly synthesized Vpr during HIV-1 infection." (PMID 34140527, 2021). "However, Vpr could induce polyubiquitination of LAPTM5 protein to prompt its degradation, consequently enhancing HIV-1 infection." (PMID 34140527, 2021). "Crucially, when we used a lentiviral shRNA targeting 3’-UTR of the LAPTM5 transcript, we found that the requirement for Vpr returned in shRNA-mediated LAPTM5-depleted MDMs, which were transduced with an LAPTM5-expression lentiviral vector during the spread of HIV-1 infection." (PMID 34140527, 2021). "HIV-1 infection is enhanced when LAPTM5 is inhibited by Vpr in macrophages, while Vpr does not enhance HIV-1 infection in the absence of LAPTM5." (PMID 39281638, 2024). "In the absence of Vpr, the silencing of LAPTM5 precisely phenocopied the effect of Vpr on HIV-1 infection." (PMID 34140527, 2021). "Vpr consistently promoted HIV-1 infection in the presence, but not absence, of LAPTM5 during 18 days of infection spreading." (PMID 34140527, 2021). "Taken together, LAPTM5 has a negative effect on the spread of HIV-1 infection of primary MDMs, whereas Vpr can overcome the inhibitory effect of LAPTM5." (PMID 34140527, 2021). "Therefore, the lack of LAPTM5 is likely to be the reason why Vpr is dispensable for HIV-1 infection of primary CD4+ T cells." (PMID 34140527, 2021).
left ventricular hypertrophy (3 papers, 2022 to 2025). Enlargement of the LEFT VENTRICLE of the heart. "In addition, LAPTM5 is a potential diagnostic marker for left ventricular hypertrophy (LVH) in hypertension, and its expression in LVH is significantly higher than that in normal controls." (PMID 40755163, 2025). "Lysosomal-associated transmembrane protein 5 (LAPTM5), involved in lysosome biogenesis and function, has been identified as a potential blood biomarker for hypertensive patients with left ventricular hypertrophy and was upregulated in insulin resistance and obesity." (PMID 36447229, 2022).
multiple myeloma (3 papers, 2017 to 2025). "We thereafter performed a series of cellular experiments to investigate the functions of LAPTM5 for drug resistance in multiple myeloma and its associated molecular pathways." (PMID 39753521, 2025). "To further investigate the role of LAPTM5‐regulated autophagy in resistance to multiple myeloma, we administered varying doses of venetoclax to both LAPTM5‐knockdown and control cells." (PMID 39753521, 2025). "In conclusion, this study elucidates the function of LAPTM5 on venetoclax resistance in multiple myeloma through its regulation of autophagy." (PMID 39753521, 2025). "Using comprehensive analyses of publicly available databases and experimental validation, we demonstrated that LAPTM5 is upregulated and enhances autophagy in recurrent multiple myeloma cells, which is a key process for cell homeostasis and drug resistance." (PMID 39753521, 2025). "Collectively, these results suggest that the overexpression of LAPTM5 promotes the venetoclax resistance, possibly via suppressing the apoptosis of myeloma cells." (PMID 39753521, 2025). "In this study, we observed that LAPTM5 expression is significantly elevated in patients with relapsed multiple myeloma, as indicated by data from the COMMPASS database." (PMID 39753521, 2025). "In relation to the involvement of LAPTM5 in neoplastic transformation, the inactivation of the LAPTM5 gene by chromosome rearrangement and DNA methylation is observed in human multiple myeloma cell lines." (PMID 28464033, 2017). "For instance, LAPTM5 might function as a tumor-suppressive protein in human multiple myeloma, yet it could also promote tumor growth in human B-cell lymphomas." (PMID 39281638, 2024). "While our study focuses on the relationship between LAPTM5 and drug resistance in multiple myeloma, it is noteworthy that our exploration of the promoting effect of LAPTM5 on autophagy revealed a positive correlation between autophagy enhancement and increased LAPTM5 protein expression." (PMID 39753521, 2025).
Obesity (3 papers, 2022 to 2026). Accumulation of substantial excess body fat. "In addition, the latest research demonstrated that LAPTM5, which is increased in obese patients, may be a hub target for obesity treatment." (PMID 35909518, 2022).
testicular germ cell tumor (3 papers, 2021 to 2024). A germ cell tumor arising from the testis. "In testicular germ cell tumor (TGCT), analysis of GEO and TCGA databases identified LAPTM5 as a potential biomarker for diagnosis and prognosis, correlating with immune infiltration in TGCT." (PMID 39281638, 2024). "A recent study showed that LAPTM5 may serve as a biomarker related to testicular germ cell tumor prognosis and diagnosis, and the survival rate was higher in the low LAPTM5 expression group, what's more, the author considered that LAPTM5 may affect the immune function." (PMID 36385959, 2022).
breast carcinoma (2 papers, 2019 to 2022). "In agreement with the findings in RCC cells, overexpression of LAPTM5 promoted the sphere formation ability of the murine 4T1luci and human MDA-MB-231 breast cancer cell lines in vitro while silencing of Laptm5 suppressed sphere formation." (PMID 35842443, 2022). "In this dataset, LAPTM5 also exhibited higher levels in breast cancer cells with high lung-specific metastatic activity (Lung-M) than in those with mediate activity (Mediate) and bone-specific metastatic activity (Bone-M)." (PMID 35842443, 2022). "For protein-coding genes, SCUBE2 and SDPR were highly expressed in the luminal A subtype, LAPTM5 and YWHAH in the HER2 subtype, and S100A11 and C6ORF211 in the luminal B subtype of breast cancer." (PMID 31801944, 2019).
Cerebral ischemia (2 papers, 2022 to 2026). Restriction of arterial blood supply to the brain associated with insufficient oxygenation to support the metabolic requirements of the tissue. "First, considering that neurons are the most vulnerable cell type after cerebral ischemia and its survival may be the key factor affecting the prognosis of stroke, so we just investigated the role of LAPTM5 in neurons in vitro." (PMID 36046710, 2022). "The LAPTM5 is involved in toll-like receptor-mediated neuroinflammation in macrophages, microglial activation in response to neuronal apoptosis, downregulation of T cell receptors and T cell activation, and may have a protective role in cerebral ischemia/reperfusion injury." (PMID 40920586, 2026). "However, the function of LAPTM5 in cerebral ischemia-reperfusion (I/R) injury has not yet been reported." (PMID 36046710, 2022).
diabetes (2 papers, 2022 to 2023). "Hence, we hypothesized that inactivation of LAPTM5 may contribute to the treatment of diabetes and its complications." (PMID 35909518, 2022). "The results of the interactions show that LAPTM5, IRF8, IGTB2, CD53, and C1QB scored higher with diabetes mellitus." (PMID 37113991, 2023).
esophageal squamous cell carcinoma (2 papers, 2016 to 2017). Esophageal squamous cell carcinoma (ESCC) is a type of esophageal carcinoma (EC) that can affect any part of the esophagus, but is usually located in the upper or middle third. "More recently, it has also been shown that LAPTM5 overexpression in human esophageal squamous cell carcinoma KYSE170 cells is able to promote release of cathepsins from lysosomes and cell death." (PMID 28464033, 2017). "Here, we found that LAPTM5 mRNA level is frequently decreased in various cancer cell lines, and its low expression in patients with esophageal squamous cell carcinoma (ESCC) and non-small cell lung cancer (NSCLC) was significantly correlated with poor prognosis." (PMID 27058622, 2016).
renal carcinoma (2 papers, 2022 to 2025). A carcinoma arising from the epithelium of the renal parenchyma or the renal pelvis. "LAPTM5 maintains the stem cell characteristics of renal cancer cells by inhibiting the function of pulmonary bone morphogenetic protein (BMP), thereby promoting lung‐specific metastasis." (PMID 40387186, 2025). "Here, we show that lysosomal protein transmembrane 5 (LAPTM5) promotes lung-specific metastasis in renal cancer." (PMID 35842443, 2022). "Together, these results established that LAPTM5 is a positive regulator of renal cancer lung metastasis." (PMID 35842443, 2022). "LAPTM5 sustains self-renewal and cancer stem cell-like traits of renal cancer cells by blocking the function of lung-derived bone morphogenetic proteins (BMPs)." (PMID 35842443, 2022). "The expression of the LAPTM5 gene in renal cancer cells is crucial for lung metastasis." (PMID 40387186, 2025). "LAPTM5 expression could also serve as an independent predictor of lung metastasis in renal cancer." (PMID 35842443, 2022). "Furthermore, in primary and metastatic RCC clinical samples, we showed that LAPTM5 negatively correlated with BMPR1A levels and predicted lung metastatic frequency in renal cancer." (PMID 35842443, 2022).